HLA-DRB5 (major histocompatibility complex, class II, DR beta 5)
Diseases named in the same sentence as HLA-DRB5 in open-access papers (continued):
Sharing a sentence is not in itself a finding about the gene and the disease.
tumor (35 papers, 2017 to 2025). "Compared to other EC subtypes,EC4 exhibited elevated expression levels of multiple genes implicated in antigen presentation (HLADRB1,HLA-DRB5,and HLA-DRA),immune cell recruitment (SELP,LIFR, and ACKR1),and anti-tumor inflammation (CCL14,IFITM1)." (PMID 41394809, 2025). "Similarly, the gene HLA-DRB5, which plays a significant role in the immune response, shows unique variants that could be implicated in the immune system's ability to recognize and respond to tumor cells." (PMID 40104216, 2025). "On the other hand, variants associated with the PSG5, HLA-DRB5 and TMCO5A genes present an opposite trend, with a higher VAF in the primary tumor and lower in metastases." (PMID 39409151, 2024). "The qRT‒PCR results revealed that the levels of HLA-DRB5 were lower and the levels of CCDC50 were higher in five high-risk tumor tissues." (PMID 36147484, 2022). "The protein levels of HLA-DRB5 were lower and the levels of CCDC50 were higher in high-risk tumor tissues." (PMID 36147484, 2022). "For example, DEG data showed, that miR-1231 induced downregulation of HLA-DRB5 (Major Histocompatibility Complex, Class II, DR Beta 5), a gene that is involved in tumor cell recognition through T lymphocytes." (PMID 35205813, 2022). "Additionally, based on the analysis of tumor epithelial cell regions, HLA-DRB5 and RASFRF1 are identified as promising molecular markers for indicating the occurrence of STAS and predicting patient prognosis." (PMID 40786043, 2025). "Higher HLA-DRB5 expression may also enhance antigen presentation, resulting in stronger and more specific anti-tumour responses." (PMID 40321251, 2025). "This study is the first to propose that the HLA-DRB5 gene in NSCLC tumor cells may inhibit the occurrence of STAS, and NSTAS samples showing high HLA-DRB5 expression potentially indicate higher immune cell infiltration and an anti-immune response." (PMID 40786043, 2025). "HLA-DRB5 has been found to be restrictive in presenting tumor antigens on CD 4+ cells." (PMID 38012322, 2023). "Notably, we found endothelial cells in stomach expressed major histocompatibility complex (MHC) class II genes such as HLA-DRA and HLA-DRB5, which was confirmed by multicolor immunohistochemistry (IHC) staining on tumor sections from GC patients." (PMID 35999201, 2022). "In summary, we propose that the expression of HLA-DRB5 in malignant EP compartments and RASGRF1 in the TN_EP compartments may be associated with the occurrence of STAS and reveal the different tumor epithelial cell-enriched compartments’ characteristics of the NSTAS and STAS groups." (PMID 40786043, 2025). "The other four genes not previously discovered to be correlated with the outcome of CM may likewise be crucial for the development of tumor, which include the interleukin receptor encoding gene IL7R, cytokine receptor FLT3, complement component C1QC, histocompatibility complex HLA-DRB5." (PMID 35300397, 2022). "Exome sequencing identified unique variants in AA patient samples within key genes, including TP73 (tumor suppression), XYLB (metabolism), ALDH4A1 (oxidative stress), PTPRB (cellular signaling), and HLA-DRB5 (immune response)." (PMID 40104216, 2025). "Our PPI network analysis identified key interactions between HLA-DRB5 and CD244, as well as HSD17B13 and CD244, as potential therapeutic targets in LUAD, with these genes showing downregulation in tumor tissues." (PMID 39092217, 2024). "Cluster Fib_5 prominently expressed MHC-II genes (HLA-DQA1, HLA-DQA2, HLA-DQB1, HLA-DRB5, HLA-DRB1, HLA-DRA, HLA-DPA1, and HLA-DPB1), indicating their role as antigen-presenting cells with tumor-suppressing effects." (PMID 37533434, 2023). "Two DEGs were identified for both the Group B/trastuzumab-sensitive models (tumor-specific antigens CTAG1B, MAGEC1) and the Group C/all treatment-sensitive models (HLA-DRB5, RNL5)." (PMID 37749105, 2023).
tumor (continued). "We applied immunohistochemistry and qRT‒PCR to detect the differences in the expression of HLA-DRB5 and CCDC50 between paired tumor tissues and normal tissues." (PMID 36147484, 2022). "Among the six TAM clusters, MHC-II TAM (cluster 14) highly expressed HLA-DRB5, APOE, and APOC1, and was more enriched in tumor core than in tumor-normal interface." (PMID 36423636, 2022). "BTK, SYK, and HLA-DRB5 were only highly expressed in PH024, and BTK is a small-molecule inhibitor which exhibited impressive anti-tumor activity in clinical studies in patients with various B-cell malignancies." (PMID 35865544, 2022). "When we compared PanCK+ tumor areas between STAS (containing TN_EP and AS_EP) and NSTAS (containing TN_EP) patients, the result revealed a significant decline in the expression of the HLA-DRB5 gene in the STAS group." (PMID 40786043, 2025). "It is worth noting that the interaction between HLA‐II molecules (such as HLA‐DRA, HLA‐DRB1, HLA‐DRB5, HLA‐DQB1, HLA‐DPB1, HLA‐DPA1, HLA‐DMB and HLA‐DMA) and the receptor CD4 was exclusively detected in the cell communication between malignant cells from single‐primary tumours and Tregs." (PMID 39601163, 2024). "Other proteins, including HLA-A, HLA-DMA, HLA-DQA1, HLA-DQB1, HLA-DRA, HLA-DRB1, and HLA-DRB5, were not reported on tumor–host immunological interactions, which indicated the proteins need further studies to testify them as novel OC biomarkers for tumor immunology." (PMID 31258820, 2019). "Compared with tumor nests in non-STAS patients, HLA-DRB5 and RASGRF1 were significantly less expressed in compartments of STAS, suggesting their inhibitory roles in the occurrence of STAS." (PMID 40786043, 2025). "However, analysis of single‐cell RNA‐sequencing (RNA‐seq) of GB patient tumors revealed that tumor cells do not express CIITA nor genes encoding for MHC‐II antigen processing (CD74, HLA‐DMA, HLA‐DOA) and presentation (HLA‐DQA1, HLA‐DQB1, HLA‐DRA, HLA‐DRB1, HLA‐DRB5)." (PMID 39535369, 2025). "In our comparison of differentially expressed genes in DCs between non-obese tumor samples and obese tumor samples, we observed significantly lower expression of certain MHC class II molecules, such as HLA-DQA2 and HLA-DRB5, in obese CRC compared to non-obese CRC." (PMID 38311726, 2024). "A similar situation was observed in the case of a KRASG12V-specific, HLA-DRB5*01:01–restricted TCR, which could recognize HLA-matched B cells, but not MHC-II–expressing tumor cells, when antigen was directed to the MHC-II presentation pathway." (PMID 36512410, 2023). "We further evaluated read depth data in tumours with an HLA-DRB5 SVs but lacking a CNV using an additional copy segmentation algorithm, finding evidence of a corresponding change number change within 2,000 bp an SV breakpoints in every tumour." (PMID 34753926, 2021).
cancer (16 papers, 2017 to 2025). A tumor composed of atypical neoplastic, often pleomorphic cells that invade other tissues. "In addition, CD44 and HLA-DRB5 which are directly interacted with HLA-A are known to be implicated by interferon signals in different cancers." (PMID 31856847, 2019). "Remarkably, IL7R, FLT3, C1QC, and HLA-DRB5 were all negatively correlated with cancer purity." (PMID 35300397, 2022). "The main pathways of methylome biomarkers were associated with calcium signalling (CACNA1E, RYR2, RYR3), cancer pathways (DCC, RASSF1, WNT1, CTNNA2), multiple neurodegenerative diseases (WNT1, DNAI1, RYR2, RYR3), immune system disorders and cell adhesion (HLA-DRA, HLA-DRB1, HLA-DRB5)." (PMID 40524349, 2025). "To quantify this finding, we developed an HLA‐DR score based on all upregulated HLA‐DR genes (HLA‐DRA, HLA‐DRB1, and HLA‐DRB5) and found that HBV cancer cells exhibited significantly higher HLA‐DR scores than NBNC cancer cells." (PMID 40464412, 2025). "When comparing NACT-treated samples with untreated ones in cancer patients the expression of TMEM51, NOTCH1, EEPD1, MAFB, and HLA-DRB5 remained increased in monocytes of treated patients." (PMID 39315092, 2024). "Notably, HLA-A, HLA-DPA1, HLA-DQB1, HLA-DRA, HLA-DRB1, HLA-DRB5, and HLA-J consistently negatively correlated with the PLK1 expression in the 12 cancer types." (PMID 30631355, 2018). "Interestingly, Type II Alveolar Epithelial Cells specifically enrich for the SECISBP2L gene in adjacent non-cancerous tissues, while HLA-DRB5 gene is enriched in cancer tissues." (PMID 39092217, 2024). "Due to the involvement of HLA-DRB5 in the processing and presentation of inflammatory and immune-related antigens processing and presentation, HLA-DRB5 may have a predictive value for survival rates of patients with malignant tumors." (PMID 36253800, 2022).
neurogenetic diseases (1 paper, 2024). "Regarding cDC1s, the genes associated with MHC II antigen presentation (HLA-DRB5, IFI30), immune activation (NAPSB), and developmental and neurogenetic diseases (NBPF14) were highly expressed in active TAO compared to NCs." (PMID 38728262, 2024).
HLA-DRB5 also shares sentences with these, for which no sentence is quoted: infection (3 papers); neurological diseases (3); allergic disease (2); breast carcinoma (2); celiac disease (2); chronic hepatitis B infection (2); glioma (2); Hodgkins lymphoma (2); immune diseases (2); narcolepsy (2); systemic lupus erythematosus (2); acute graft versus host disease (1); adenocarcinoma (1); adult onset asthma (1); Allergy (1); atherosclerosis (1); autoimmune disorders (1); autoimmune PAP (1); autoimmune thyroid disease (1); cervical tumor (1); channelopathies (1); childhood onset asthma (1); Chlamydia infections (1); chronic lymphocytic leukaemia (1); cognitive decline (1); colon adenocarcinoma (1); Crohn disease (1); demyelinating disease (1); dengue (1); dilatation (1).
A further 29 diseases each share a sentence with HLA-DRB5 in 1 paper.